MIR181A1HG (MIR181A1 host gene)
Gene: Long non-coding RNA gene on chromosome 1 (198,739,203 to 198,937,683, reverse strand). Ensembl gene ENSG00000229989.
Gene Ontology:
Biological process: miRNA-mediated post-transcriptional gene silencing
Cellular component: RISC complex
Diseases named in the same sentence as MIR181A1HG in open-access papers:
MIR181A1HG is named in the same sentence as 4 diseases in open-access papers, as found by Europe PMC text mining. Sharing a sentence is not in itself a finding about the gene and the disease. The quoted sentences say what the papers report.
atherosclerosis (1 paper, 2023). A disease characterized by the build-up of fatty material and calcium deposition in the arterial wall resulting in partial or complete occlusion of the arterial lumen. "Molecular docking revealed most DSY bioactive components can bind key EndMT-related lncRNAs, including AC003092.1, MIR181A1HG, MIR155HG, WEE2-AS1, and MIR137HG, suggesting DSY may mitigate EndMT in atherosclerosis by modulating the ceRNA network." (PMID 38268851, 2023).
MIR181A1HG also shares sentences with these, for which no sentence is quoted: cancer (2 papers); leukemia (1); tumor (1).